ABCA1 (ATP binding cassette subfamily A member 1)
Diseases named in the same sentence as ABCA1 in open-access papers (continued):
Sharing a sentence is not in itself a finding about the gene and the disease.
Stroke (continued). "Limitations: The present study is not an investigation of a stroke treatment; it is a proof-of-concept study that mainly focuses on mechanisms underlying the ABCA1/ApoE/HDL pathway in mediating myelination during stroke repair." (PMID 32575457, 2020). "Besides, ABCA1 modulates a variety of brain functions, such as neuroinflammation (a crucial process following stroke) and blood-brain barrier leakage, and both these two are key factors to worsen stroke outcomes." (PMID 40264650, 2025). "Thus, the ABCA1/ApoE/HDL signaling pathway may provide a new clinical strategy for improving neurological functional recovery after stroke." (PMID 32575457, 2020). "However, the downstream molecular mechanism underlying brain ABCA1-deficiency-induced deficits after stroke is not fully understood." (PMID 30373276, 2018). "Adult male ABCA1−B/−B and ABCA1-floxed control mice were subjected to distal middle-cerebral artery occlusion and were intraventricularly infused with artificial mouse cerebrospinal fluid as vehicle control or recombinant human ApoE2 into the ischemic brain starting 24 h after stroke for 14 days." (PMID 30373276, 2018). "Therefore, in this study, we employ middle-aged, brain-ABCA1 deficient (ABCA1−B/−B) and ABCA1-floxed (ABCA1fl/fl) control mice that were induced with T2DM and subjected to stroke, to test whether L-4F treatment initiated at 24 h after onset of ischemic stroke enhances neurological recovery." (PMID 35572941, 2022). "Our data indicate that the ABCA1/ApoE/HDL signaling pathway contributes to myelination and oligodendrogenesis in the ischemic brain after stroke." (PMID 32575457, 2020). "Previous study demonstrated that the deletion of brain ABCA1 significantly reduces brain ApoE and HDL content, and it decreases myelin density and OLs and OPCs in the ischemic brain after stroke." (PMID 32575457, 2020). "Upregulation of ABCA1 is involved in the effects of LXR agonists in decreasing neuroinflammation, facilitating neuroprotection, and improving neurological functional-outcomes post stroke." (PMID 40264650, 2025). "Two transporters, ABCA1 and ABCG1, may protect against heart disease and stroke by removing excess cholesterol from artery cells." (PMID 40906448, 2025). "A major cell type in arteries that accumulates cholesterol is macrophages, and it is thought that increasing ABCA1/ABCG1 expression specifically in macrophages within arteries may protect against heart disease and stroke." (PMID 40906448, 2025). "Our results indicate that inhibition of brain ABCA1 does not attenuate the neurorestorative benefits induced by L-4F treatment in ABCA−B/−B-T2DM stroke mice." (PMID 35572941, 2022). "Here, we investigate whether ABCA1/ApoE/HDL contribute to myelin repair and oligodendrogenesis in the ischemic brain after stroke." (PMID 32575457, 2020). "This study along with previous studies suggests that L-4F derived therapeutic effects in brain rewiring after stroke injury may, at least partially, be independent of the ABCA1, ApoE, or ApoA-I." (PMID 35572941, 2022). "In this study, using ABCA1-B/-B mice, we further investigate whether ABCA1, ApoE, and the HDL signaling pathway mediate axonal myelination and contribute to oligodendrogenesis and WM remodeling in the ischemic brain after stroke." (PMID 32575457, 2020). "In human blood, the expression of ABCA1 mRNA was significantly upregulated in stroke patients compared to non-stroke controls, suggesting that increased ABCA1 expression may contribute to cell protection after ischemic injury and prevent further cellular damage." (PMID 34131232, 2021). "However, whether L-4F is capable of crossing the BBB and whether long-term post-stroke treatment with L-4F promotes neurovascular and WM remodeling and improves recovery of neurological function in T2DM, and whether ABCA1 mediates L-4F-induced neurorestoration have not been studied." (PMID 35572941, 2022).
colorectal cancer (16 papers, 2015 to 2025). A primary or metastatic malignant neoplasm that affects the colon or rectum. "Together, these data support our previous results obtained in two‐dimensional cultures, suggesting that overexpression of ABCA1 could be associated with increased invasive capacities in colorectal cancer‐derived cells." (PMID 30098223, 2018). "Moreover, decreased ABCA1 activity has been reported in colorectal cancer cells either through loss-of-function or gene downregulation and ABCA1 downregulation promoted cancer cell survival by increased mitochondrial cholesterol accumulation." (PMID 27455839, 2016). "ABCA1 overexpression stabilizes Cav1 in colorectal cancer, leading to increased invasive capacities." (PMID 39049847, 2024). "Current research on OSBPL1A is limited, but existing studies suggest that it influences the production of HDL-C in the liver and intestines in conjunction with ABCA1 and also acts as a crucial prognostic factor in colorectal cancer." (PMID 38440405, 2024). "ABCA1 has been shown to play a crucial role in the development of resistance and proliferation of colorectal cancer." (PMID 37324492, 2023). "Apolipoprotein A1 (APOA1), located in the Ch 11q deleted region, was previously reported as an inhibitor of COX-2 expression in colorectal cancer, which results in the negative regulation of phospholipid-transporting ATPase ABCA1." (PMID 36471782, 2022). "ABCA1 is significantly overexpressed in patients in advanced stages of colorectal cancer, and its overexpression confers proliferative advantages by regulating CAV-1 stability." (PMID 36471782, 2022). "One study revealed that upregulation of genes (ABCA1, ACSL1, AGPAT1, and SCD) related to lipogenesis and cholesterol synthesis pathways was associated with poor survival outcomes in colorectal cancer patients." (PMID 34557266, 2021). "For example, in colorectal cancer cell lines, ABCA1 overexpression led to an epithelial-to-mesenchymal transition and stabilized caveolin-1, known to promote cell migration, invasion, and has been proposed to be involved in tumor cell metastasis." (PMID 33562440, 2021). "On the other hand, ABCA1 has been classified as a member of a lipid metabolism gene expression signature (ColoLipidGene) related to poor prognosis in patients with colorectal cancer (CRC)." (PMID 33562440, 2021). "The expression levels of the cholesterol transporter ABCA1 can be considered new prognosis markers for colorectal cancer malignancy." (PMID 30098223, 2018). "ABCA1 is significantly overexpressed in patients at advanced stages of colorectal cancer, and its overexpression confers proliferative advantages together with caveolin‐1 dependent‐increased migratory and invasive capacities." (PMID 30098223, 2018). "Here, we present the ATP‐binding cassette transporter (ABCA1), a regulator of cholesterol transport, as a new marker for invasion and colorectal cancer survival." (PMID 30098223, 2018). "Thus, ABCA1 overexpression might lead to a stabilization of CAV‐1 protein in patients with colorectal cancer, leading to increased invasive capacities of tumour cells." (PMID 30098223, 2018). "The genomic coding sequence of ABCA1, ACSL1, AGPAT1 and SCD genes, as well as, their differential expression in a genome-wide expression meta-analysis in colorectal cancer patients were explored." (PMID 29464044, 2018). "YY1 cooperates with transcriptional coactivator PGC-1α and then enhances transcriptional activity of the ATP-binding cassette transporter 1 (ABCA1) gene, resulting in elevated ABCA1 expression levels, leading to insensitivity of colorectal cancer cells to isoliquiritigenin and tumor metastasis." (PMID 40867514, 2025).
dementia (16 papers, 2010 to 2025). Loss of intellectual abilities interfering with an individual's social and occupational functions. "Patients with the ABCA1 (rs2230806) GG variant presented a shorter dementia duration compared to those with the AA and GA genotypes (p = 0.0001 and p = 0.0004, respectively)." (PMID 41226793, 2025). "Polymorphisms in ABCA1 have been demonstrated to influence susceptibility to dementia, in particular to AD." (PMID 36570531, 2022). "As for dementias, in experimental models, ABCA1 activities appear to influence neuroinflammation and neurodegeneration, thus possibly affecting different forms of dementia, including FTD." (PMID 36570531, 2022). "In AD patients, mRNA and protein level of ABCA1 is reported positively correlated with severity of dementia, which may be due to ABCA1‐mediated disruption of lipid architecture thus disturb cellular activities." (PMID 39548663, 2024). "Increased expression of ABCA1 is highly correlated with severity of dementia in AD HIP." (PMID 24628925, 2014). "Increased levels of ABCA1 and ApoE may be the molecular determinants of cholesterol dyshomeostasis and accompanying dementia observed in AD." (PMID 20843353, 2010). "In addition, changes in LXR/RXR target genes, ABCA1 and ApoE in AD brains as a function of the increasing severity of dementia and neurofibrillary pathology were also observed." (PMID 20843353, 2010).
Hepatic steatosis (16 papers, 2015 to 2025). Steatosis is a term used to denote lipid accumulation within hepatocytes. "Human studies also suggest the elevation of TG levels usually develop fatty liver disease, and there is an inverse association between TG concentrations and dysfunctional ABCA1." (PMID 36005631, 2022). "In addition, a study also reported when the function of ABCA1 is diminished, the TG secretion from liver increased, suggesting there is a strong association between ABCA1 and fatty liver disease." (PMID 36005631, 2022). "As a result, stimulation of the ABCA1/apoA-I pathway can decrease the lipid levels in hepatocytes, which in turn causes a decrease in ER stress levels as well as the expression levels of lipogenic genes, eventually resulting in a reduction in hepatic steatosis." (PMID 28577569, 2017). "Several reports have indicated that the secretion of TG and accumulation of lipids in hepatocytes is significantly increased after blocking the ABCA1 function, pointing out the close relationship between ABCA1 expression and fatty liver disease." (PMID 35057469, 2022). "ATP-binding cassette transporter A1 (ABCA1) is a key regulator of lipid efflux, and the absence of ABCA1 induces hepatic lipid accumulation, which is one of the major causes of fatty liver." (PMID 35057469, 2022). "further demonstrated that ABCA1 could mediate the transport of cholesterol and phospholipids from cells to high-density lipoprotein apolipoprotein, thereby affecting the transport of liver cholesterol and inducing fatty liver disease." (PMID 36033523, 2022). "All patients were subjected to liver function tests, lipids profile, triglyceride TG index, and hepatic steatosis index (HSI) and real‐time PCR ABCA1 SNP (rs1800977)." (PMID 36444680, 2023). "Relative to wild-type mice, ApoE−/− mice fed an HFD exhibit reduced hepatic ABCA1 expression, whereas BBR treatment enhances the expression of ABCA1 and alleviates atherosclerotic lesions and hepatic steatosis." (PMID 38034996, 2023). "Unfortunately, ABCA1 and ABCG1 are downstream genes of LXR, activation of which can lead severe hepatic steatosis." (PMID 31938053, 2020). "All these data suggest that ALDH2 downregulated ABCA1 expression and decreased cholesterol efflux from LKO liver tissues through attenuating poly(ADP-ribosyl)ation of LXRα, which manifested as lower levels of HDL in the circulation but increased hepatic steatosis in ALKO compared with LKO mice." (PMID 35393951, 2022).
Hyperglycemia (16 papers, 2011 to 2025). An increased concentration of glucose in the blood. "Our findings suggest the association of low ABCA1 with that of lipid profile and hyperglycemia." (PMID 37821518, 2023). "In accord with the data that miR-33 and ABCA1 may be functionally linked, we showed that ABCA1 and cholesterol efflux are co-regulated by glucose and statins in macrophages, suggesting that hyperglycemia and statins seem to share a common regulatory mechanism." (PMID 27139226, 2016). "Previously, we have shown that hyperglycemia suppresses ABCA1 expression via post-transcriptional regulation in macrophages." (PMID 27139226, 2016). "Under conditions of hyperglycemia and statin treatment, microRNA-33 levels are elevated, and ABCA1 expression is decreased, which then results in a reduction in cholesterol efflux from macrophages." (PMID 27139226, 2016). "Besides, ABCA1 recycling disorders under hyperglycemia further aggravated cellular injury in podocytes." (PMID 32774146, 2020). "In the present study, we explore relationships between glycaemia, expression of ABCA1 and ABCG1, ABCA1 protein concentrations and ABCA1 function in people with varying degrees of hyperglycaemia, and whether these relationships are influenced by LXRα or PPARγ expression." (PMID 21829447, 2011). "Accumulating experimental evidence suggest that ABCA1 or ABCG1 expression in macrophages is suppressed by high-glucose concentrations in vitro and by hyperglycemia ex vivo." (PMID 28408925, 2017). "We obtained similar results, in that hyperglycemia enhanced RAGE and CD36 expression and decreased ABCA1 and ABCG1 expression." (PMID 26807573, 2016). "Fourth, UDCA reduced foam cell formation via upregulation of ABCA1 and ABCG1 expression, reduction of hyperglycemia-induced RAGE expression, and suppression of macrophage inflammatory responses." (PMID 26807573, 2016). "In the setting of hyperglycemia, AGE formation is prevalent compromising both the expressions of ABCA-1 and ABCG-1." (PMID 21957962, 2011).
diabetic nephropathy (15 papers, 2014 to 2025). "Deleting ABCA1 lead to inflammation, impaired β-cell function, mitochondrial dysfunction in podocytes, and rendered mice susceptible to diabetic kidney disease." (PMID 32774146, 2020). "CE induces renal cell damage by increasing LCAT and ACAT levels and decreasing ABCA1 levels when diabetic nephropathy (DN) is fed a high-fat diet, leading to abnormal lipid metabolism." (PMID 40268915, 2025). "CCDC92 promotes podocyte lipotoxicity by dysregulating lipid homeostasis via ABCA1 signaling, leading to lipid accumulation and podocyte damage in diabetic kidney disease." (PMID 41009556, 2025). "We have investigated the role of cellular cholesterol transport proteins including adenosine triphosphate binding cassette transporter A1 (ABCA1), G1 (ABCG1) and scavenger receptor class B type I (SR-BI) in diabetic nephropathy." (PMID 25181357, 2014). "Decreased ATP Binding Cassette Transporter A1 (ABCA1) expression and caspase-4-mediated noncanonical inflammasome contribution have been described in podocytes in diabetic kidney disease (DKD)." (PMID 37316538, 2023).
lung carcinoma (14 papers, 2013 to 2024). "In line with this, Kaplan–Meier Plotter analysis showed that low ABCA1 expression was associated with poor survival in lung cancer patients." (PMID 39349433, 2024). "For examples, simvastatin re-polarized TAMs, promoted M2-to-M1 phenotype switch, and suppressed epithelial-mesenchymal transition in lung cancer via cholesterol-associated LXR/ABCA1 regulation." (PMID 37484027, 2023). "Conversely, exposure of H1299 lung cancer cells to escalating doses of α-Tocopheryl succinate made these cells resistant to the agent due to the upregulation of the ABCA1 protein, which caused its efflux." (PMID 32577155, 2020). "Treatment with valproic acid (VPA) enhanced cisplatin sensitivity of non-small-cell lung cancer (NSCLC) cells via HDAC2 mediated down-regulation of ABCA1, further reinforcing the idea that overexpression of ABCA1 in lung cancer can be associated with resistance to therapies." (PMID 34281263, 2021). "Additionally, overexpression of ABCA1 is associated with resistance to several medications in breast and lung cancer, including curcumin, doxorubicin, nitidine, and more." (PMID 34281263, 2021). "The result showed that gilteritinib-induced cholesterol accumulation almost disappeared in lung cancer cells with overexpression of ABCA1, suggesting that the cholesterol is discharged out of the cell by the overexpressed ABCA1." (PMID 39349433, 2024). "RASSF1C was shown to downregulate miR-33a in lung cancer cells, therefore derepressing ABCA1 and ABCG1 transporters." (PMID 34281263, 2021). "Meanwhile, synergetic effects of efatutazone and T0901317 on lung cancer cells proliferation inhibition and PPARγ/LXRα/ABCA1 pathway activation were also proved." (PMID 29573196, 2018). "ABCA1 has also been identified as mediating drug resistance in lung cancer and drug-resistant lung cancer cell lines." (PMID 26270652, 2015). "As abnormal metabolism is generally found in cancer, ABCA1 deserves further investigation with regard to its role in lung cancer." (PMID 23762832, 2013). "Notably, IHC analysis revealed that higher expression of ABCA1 was observed in the paraffin-embedded archived lung cancer specimens compared to the normal tissues." (PMID 39349433, 2024). "In addition, we employed immunohistochemistry (IHC) to detect the protein expression of ABCA1 in 30 pairs of lung cancer tissues and normal lung tissues." (PMID 39349433, 2024). "Furthermore, ABCA1 protein also is upregulated by 25HC treatment in the two lung cancer cells (top row)." (PMID 39349433, 2024). "Moreover, downregulation of ABCA1 (ATP-binding cassette transporter A1) promoted the cytotoxicity of nitidine in lung cancer cells." (PMID 33288736, 2020). "The up-regulation of ABCA1 was validated in normal lung epithelial and lung cancer cells by RT-PCR." (PMID 30719208, 2019). "Our data indicated that PPARγ affected cell growth of lung cancer cells expressing LXRα and ABCA1, we attempted to examine whether PPARγ regulated the expression of LXRα and ABCA1." (PMID 29573196, 2018). "A recent report indicates that the use of mitochondrially targeted drugs could counteract ABCA1-dependent resistance of the lung carcinoma cells." (PMID 23764021, 2013). "Indeed, in lung cancer cells, simvastatin remodels TME and reverses epithelial-mesenchymal transition (EMT) by re-polarizing tumor-associated macrophages (TAMs) from M2 to M1 via cholesterol-associated LXR/ABCA1 regulation." (PMID 37484027, 2023). "Analysis of these shortest path genes indicates that some of these genes, such as ESR1, FDXR, ABCA1, IRS1, HSP90AA1, FOXM1, and IGBP1 are related to lung cancer." (PMID 23762832, 2013). "Among 70 consecutively enrolled patients (nonsmall cell lung cancer: 94%; renal cell carcinoma: 6%), TC, CLC, and cholesterol PD resulted significantly higher in IL-6low and IL-10low cases (P<0.05), whereas ABCA1-mediated CE was increased in IL-10high patients (P=0.018)." (PMID 38989743, 2024).
lung carcinoma (continued). "Using data from our previous Microarray studies, we checked the expression levels of ABCA1 in cell lines over-expressing RASSF1C and we found that RASSF1C over-expression in both breast and lung cancer cell lines resulted in a significant increase in the expression level of ABCA1." (PMID 30719208, 2019). "We investigated indices of cholesterol metabolism (total cholesterol, ABCA1, ABCG1, PD, and cholesterol loading capacity [CLC]) together with clinical outcome and systemic inflammatory status in patients with advanced renal and lung cancer treated with immunotherapy." (PMID 38989743, 2024). "Thus, it is possible that RASSF1C down regulation of miR-33a results in up-regulation of ABCA1 gene expression could be a mechanism through which RASSF1C enhances breast and lung cancer cell drug resistance." (PMID 30719208, 2019).